PLUT (PDX1 associated lncRNA, upregulator of transcription)
Synonyms: PLUTO; HI-LNC71; formerly PDX1-AS1
Gene: Long non-coding RNA gene on chromosome 13 (27,819,376 to 27,917,298, reverse strand). Ensembl gene ENSG00000247381.
Diseases named in the same sentence as PLUT in open-access papers:
PLUT is named in the same sentence as 9 diseases in open-access papers, as found by Europe PMC text mining. Sharing a sentence is not in itself a finding about the gene and the disease. The quoted sentences say what the papers report.
lung adenocarcinoma (1 paper, 2022). A carcinoma that arises from the lung and is characterized by the presence of malignant glandular epithelial cells. "For instance, promoter hypermethylation of the lncRNA PLUT was significantly associated with shorter relapse-free survival of lung adenocarcinoma, and hypermethylated ZNF667-AS1 was correlated with ESCC patients’ survival." (PMID 36064442, 2022).
adenocarcinoma (1 paper, 2021). A common cancer characterized by the presence of malignant glandular cells. "Promoter hypermethylation of the lncRNA PLUT is predictive in patients with early stage I adenocarcinoma at high risk for early recurrence." (PMID 34307152, 2021).
cancer (1 paper, 2021). A tumor composed of atypical neoplastic, often pleomorphic cells that invade other tissues. "Both upregulation and downregulation of lncRNAs involved in many physiological processes, such as MALAT1, PLUT, and CARMN, are associated with the onset of various cancers, as well as metabolic, cardiovascular, and neurological disorders." (PMID 33925370, 2021).
PLUT also shares sentences with these, for which no sentence is quoted: Impaired glucose tolerance (3 papers); type 2 diabetes (3); diabetes (1); neurological disorders (1); pancreatic cancer (1); thiamin deficiency (1).